PAX6 (paired box 6)
Diseases named in the same sentence as PAX6 in open-access papers (continued):
Sharing a sentence is not in itself a finding about the gene and the disease.
aniridia (continued). "They examined the Human PAX6 Allelic Variant Database and found that three-quarters of aniridia cases were caused by mutations that introduced premature termination codons into the PAX6 open reading frame." (PMID 17417613, 2007). "Because the vast majority of aniridia cases in man are caused by mutations in the PAX6 gene we used the candidate gene approach to evaluate PAX6 in the study population." (PMID 17417604, 2007). "Experimentally induced mutations in mouse Pax6 exhibit a range of phenotypes, including partial to complete aniridia, iris abnormalities, cataract, and corneal adhesions." (PMID 17417604, 2007). "We cloned and characterized canine PAX6, and evaluated PAX6 for causal associations with inherited aniridia in dogs." (PMID 17417604, 2007). "One MRI study showed the absence or hypoplasia of the pineal gland and absence or hypoplasia of the anterior commissure are common in patients who have aniridia and known PAX6 mutations with diverse ocular abnormalities." (PMID 17417613, 2007). "Mutations in the paired-box 6 (PAX6) gene cause aniridia in man, a panocular disorder primarily characterized by complete or partial absence of iris tissue." (PMID 17417604, 2007). "This mutation is a recurrent protein truncation mutation that is always associated with aniridia, as seen in a search of the Human PAX6 Allelic Variant Database." (PMID 17417613, 2007). "In many affected patients from Group 1, we did not detect any mutations in exons of the PAX6 gene, although PAX6 is, thus far, the only gene associated with aniridia." (PMID 17417613, 2007). "Recent studies using MRI, moreover functional MRI, have shown that individuals with aniridia and cognition deficits due to a heterozygous mutation in PAX6 have structural abnormalities of the grey matter as well as white matter deficits in the corpus callosum." (PMID 17417613, 2007). "We screened for PAX6 mutations in genomic DNA from nine Indian pedigrees with familial aniridia in which more than one person was affected." (PMID 16803629, 2006). "This study was performed to identify novel PAX6 mutations that lead to familial aniridia in Indian patients." (PMID 16803629, 2006). "We therefore present an analysis of five Indian pedigrees out of nine with hereditary aniridia demonstrating four novel mutations and one previously reported nonsense genetic alteration of PAX6." (PMID 16803629, 2006). "The c.393insTCAGC insertion in ANF8-1 is novel, but a c.395delC mutation with familial aniridia was previously reported which lies in same codon of PAX6 but two base pairs down." (PMID 16803629, 2006). "Haploinsufficiency at the PAX6 locus causes aniridia, a panocular eye condition characterized by iris hypoplasia and a variety of other anterior and posterior eye defects leading to poor vision." (PMID 16803629, 2006). "In this study, five mutations were found in PAX6 in affected members from nine unrelated families with inherited aniridia." (PMID 16803629, 2006). "Congenital aniridia caused by heterozygousity at the PAX6 locus is associated with ocular surface disease including keratopathy." (PMID 16914058, 2006). "In humans, PAX6 haploinsufficiency is the cause of the congenital eye malformation aniridia, and has more recently also been shown to cause brain defects." (PMID 17014839, 2006). "PAX6 mutations also cause a range of non-aniridia phenotypes such as optic nerve defects, keratitis, microphthalmia, and foveal hypoplasia." (PMID 15918896, 2005). "The consistent association of truncating mutations with the aniridia phenotype, and the distribution of truncating mutations in the PAX6 open reading frame, suggests that nonsense-mediated decay acts on PAX6 mutant alleles." (PMID 15918896, 2005). "The small eye (Sey) mouse carries a Pax6 nonsense variant (c.580G>T, p.G194X), presenting with microphthalmia, aniridia, and other ocular phenotypes like human aniridia, making it a critical model for studying aniridia pathophysiology and therapies." (PMID 41328347, 2026).
aniridia (continued). "Pathogenic variants in PAX genes underlie diverse congenital disorders such as aniridia (PAX6), renal coloboma syndrome (PAX2), otofaciocervical syndrome with immunodeficiency (PAX1), Waardenburg syndrome (PAX3), maturity-onset diabetes of the young (PAX4), and tooth agenesis (PAX9)." (PMID 41751498, 2026). "In partial loss-of-function Pax6 mutants, early eye development appears relatively normal, but by the tadpole stage, the iris shows developmental deficiencies similar to the typical phenotype of aniridia in human PAX6 mutation carriers." (PMID 41210874, 2025). "Variants resulting in aberrant splicing of the PAX6 5′UTR are a frequent cause of aniridia." (PMID 40229884, 2025). "Congenital aniridia is a bilateral, panocular disorder with an estimated incidence of 1:50,000–1:100,000 live births and is primarily due to haploinsufficiency of the paired box 6 (PAX6) gene, which results from an autosomal dominant mutation on chromosome 11." (PMID 40622913, 2025). "Moreover, Cas9 RNP-loaded LNPs corrected the Sey variant and restored FLAG-tagged PAX6 expression in 38% of ex vivo cortical neurons derived from a mouse model of aniridia, known as Small eye (Sey)." (PMID 40006568, 2025). "A rare case of an isolated PAX6 mutation causing both aniridia and WT has previously been reported." (PMID 40439002, 2025). "Nevertheless, it is estimated that there are currently about 940 patients in Germany with the diagnosis “congenital aniridia” (about 85% may be PAX6-associated aniridia)." (PMID 37647922, 2024). "Variations in PAX6 and its adjacent regions were the predominant causes of aniridia in China." (PMID 39449022, 2024). "In humans, mutations in the Pax6 gene are linked to aniridia and aniridia-related keratopathies." (PMID 38247854, 2024). "In addition to aniridia, PAX6 mutations can also cause foveal dysplasia or affect only the fovea without the involvement of the iris, which is a rare medical condition involving the underdevelopment of the macula." (PMID 39449022, 2024). "Mutations in PAX6 cause a range of developmental disorders (reviewed here), with homozygous deletions being lethal in mice and humans, while heterozygous deletions, nonsense, and frameshift mutations typically cause aniridia in humans." (PMID 38849565, 2024). "In addition to intragenic point mutations in PAX6, deletion of PAX6 or its adjacent genes is a common cause of congenital aniridia." (PMID 39449022, 2024). "Moreover, the available clinical features of PAX6-associated aniridia in this study were investigated." (PMID 36983625, 2023). "Therefore, the defects of RB, E180B, and HS elements are likely to be the underlying cause of familial aniridia by affecting the PAX6 expression in this Chinese family." (PMID 37752489, 2023). "Heterozygous mutations in the PAX6 gene or its regulatory regions cause aniridia." (PMID 37752489, 2023). "For example, mutations in FOXC1 (forkhead box transcription factor C1) and PITX2 (paired-like homeodomain transcription factor 2) were found in Axenfeld–Rieger syndrome; genotype–phenotype mutations in PAX6 (paired box 6) were found to be associated with aniridia." (PMID 36832310, 2023). "Additionally, there is increasing evidence that defects in PAX6 pre-mRNA splicing represent a major cause of aniridia, with more than 100 described splicing variants accounting for up to 15% of disease-causing variants." (PMID 36675087, 2023). "Nowadays, pathogenic PAX6 variants are identified in ~90% of patients with classical aniridia." (PMID 37269011, 2023). "It is known that mutations of the PAX6 gene can cause aniridia." (PMID 37510387, 2023). "In 1991, PAX6 was identified as the causative gene of congenital aniridia by positional cloning." (PMID 37542296, 2023). "Although other disease-associated loci may remain to be discovered in congenital aniridia, PAX6 inversions or other complex SVs may have been missed during genetic analysis in unsolved cases." (PMID 37269011, 2023).
aniridia (continued). "As mentioned in the previous sections, mutations of PAX6 may lead to various ocular disorders, including congenital aniridia and hypoplasia of the fovea and optic nerve." (PMID 36816037, 2023). "A large part of patients carrying PAX6 mutations presented with aniridia phenotypes." (PMID 36843716, 2023). "This study demonstrates that this frameshift mutation of the PAX6 gene might be the causative genetic defect of congenital aniridia in this family." (PMID 36983625, 2023). "Aniridia may also be caused by large genomic deletions encompassing PAX6 and Wilms tumor 1 (WT1), contiguous genes separated from each other by 700 kb, resulting in WAGR syndrome." (PMID 37542296, 2023). "PAX6 homozygous variants typically give rise to aniridia or anophthalmia; but missense variants (nearly 12%) may result in milder phenotypes including isolated foveal hypoplasia, Peter’s anomaly, partial aniridia, optic nerve defect and bilateral cataract." (PMID 34345029, 2022). "Also, mutations in human PAX6 lead to numerous eye defects, including aniridia, corneal opacification, and cataract." (PMID 36007075, 2022). "Aniridia, leading to a variable degree of iris and foveal hypoplasia, nystagmus, cataract, glaucoma and corneal keratopathy usually affects 1:40,000–100,000 births and is caused by PAX6 variants." (PMID 35911417, 2022). "A large cohort of 199 patients from Russia with aniridia or aniridia-related phenotypes was studied for the PAX6 mutation spectrum, considering the background of the PAX6 mutation spectrum in the world’s population and the ratio of de novo mutations in the whole genome." (PMID 35743132, 2022). "Recently in families with congenital aniridia it has been suggested that PAX6 mutations and glucose metabolism may be associated; with case-control suggesting that the production of proinsulin to insulin may include participation from the PAX6 gene." (PMID 34970513, 2021). "The present study expanded the mutation spectrum of the PAX6 gene which may be helpful in the genetic diagnosis of aniridia." (PMID 34016071, 2021). "A high proportion of cases of aniridia was associated with mutations in PAX6 frameshift mutations, splicing site mutations or nonsense mutations and these kinds of variations have been considered to produce premature truncation of the protein or nonsense transcripts, leading to haploinsufficiency." (PMID 34016071, 2021). "One study reported 5 unrelated patients with aniridia, 4 of which had PAX6 mutations, all with either glucose intolerance or diabetes; however, the causal relationship for diabetes remains unclear, as the majority of patients with aniridia do not develop it." (PMID 34101622, 2021). "In brief, a novel nonsense mutation in PAX6 (c.619A > T p.K207*) was identified in a Chinese family with aniridia, which could cause PAX6 haploinsufficiency." (PMID 34016071, 2021). "Our results suggest that, while obesity may have an effect on the development of diabetes in some patients with aniridia, the presence of PAX6 mutations is a likely factor." (PMID 34101622, 2021). "Furthermore, though variants in PAX6 are typically connected with aniridia, a small number of bilateral and unilateral microphthalmia/coloboma cases have been identified, with or without aniridia." (PMID 33973683, 2021). "It has been demonstrated that occurrence of PAX6 mutations may result in the development of aniridia, which constitutes a severe panocular eye disease associated with iris hypoplasia." (PMID 32545285, 2020). "Notably, in vertebrates, Pax6 function is also hallmarked by gene dosage, and aniridia in humans is linked with mutations that lead to Pax6 haploinsufficiency." (PMID 33425902, 2020). "However, phenotypic variation of the same Pax6 gene mutation has shown both aniridia and PA within one family, and PA has been associated with aniridia in more than 10% of cases." (PMID 33425902, 2020).
aniridia (continued). "Ataluren (1% m/v) suspension in 0.9% saline vehicle containing 1% tween 80 as a co-solvent, and 1% carboxymethylcellulose to increase viscosity, also known as the ‘START’ formulation, was shown to rescue the corneal deficit in Pax6-deficient mice model of aniridia." (PMID 33375041, 2020). "Notably, PAX6 mutations in humans also underlie a variable pan-ocular phenotype(s) including aniridia (iris hypoplasia), foveal hypoplasia, anterior segment dysgenesis 5 (ASD5), late-onset corneal dystrophy, ocular coloboma, and congenital cataract." (PMID 32070426, 2020). "Notably, mutations in Pax6 are more typically associated with aniridia, a panocular congenital disease characterized by foveal hypoplasia, optic nerve hypoplasia, limbal stem cell deficiency, and varying degrees of iris hypoplasia." (PMID 33425902, 2020). "This is important for developmental eye disorders, such as aniridia where ~15% of all PAX6 variants are located in intronic regions, with the majority at the intron–exon border (Lima Cunha, Arno, Corton, & Moosajee, 2019), although only 8.6% were noncoding variants from the WGS group in this study." (PMID 32830442, 2020). "PAX6 is a transcription factor most commonly associated with aniridia." (PMID 31416264, 2019). "Of these nine aniridia cases, seven had known congenital glaucoma (one unknown), many presenting as infants with buphthalmos, suggesting that this is more common in FOXC1- than PAX6-associated aniridia." (PMID 30242502, 2019). "Hence, it was concluded that a novel deletion in the PAX6 gene was identified in a Chinese family associated with aniridia, which expands the spectrum of the PAX6 mutation and its associated phenotype." (PMID 30621664, 2019). "Aniridia is an autosomal dominant disorder that is marked by the complete or partial absence of the iris, foveal hypoplasia, and nystagmus, and is caused by heterozygous PAX6 mutations." (PMID 31861090, 2019). "Here, we describe 3 families with variable inter-generational ocular expression of aniridia, iris coloboma, or microphthalmia, and an unusual transmission of PAX6 mutations from an unaffected or mildly affected parent; all of which raised suspicion of gonosomal mosaicism." (PMID 30386378, 2018). "Thus, it is predicted to be a complete loss of a function PAX6 allele, consistent with the aniridia phenotype." (PMID 29850208, 2018). "It suggests that mutations in the other genes, yet undiscovered genetic loci or unknown mechanisms disrupting the PAX6 gene function could be the cause of aniridia." (PMID 29460221, 2018). "PAX6 haploinsufficiency, which results from loss-of-function variants or 11p13 microdeletions involving this gene or their 5′ regulatory regions, is the major cause of congenital aniridia (MIM# 106210)." (PMID 30386378, 2018). "To date, 221 mutations in PAX6 have been reported; most are associated with aniridia, though some mutations are associated with other ocular diseases such as coloboma, morning glory disc anomaly, anterior segment dysgenesis, and cataract with late-onset corneal dystrophy (ClinVar: PAX6[gene])." (PMID 29850208, 2018). "So the p.P375R mutation of PAX6 is likely to be benign for congenital aniridia." (PMID 30334364, 2018). "Additionally, we demonstrate for the first time that mosaic PAX6 variants cause phenotypic variability from congenital aniridia, mild forms of isolated iris coloboma, and even asymptomatic individuals." (PMID 30386378, 2018). "PAX6 is the main disease‐causing gene of congenital aniridia; inheritance is autosomal dominant." (PMID 30334364, 2018). "Additional studies, which include a larger number of individuals with aniridia, are required to better understand whether PAX6 mutations also have phenotypic variability in regards to glucose regulation." (PMID 29850208, 2018).
aniridia (continued). "According to our findings and those reported using CRISPR models, somatic PAX6 mosaicism might explain some of the approximately 10% of patients with aniridia who apparently lack PAX6 mutations or even mild cases of ODAs." (PMID 30386378, 2018). "Congenital aniridia with cataract is linked to a mutation of the PAX6 genes." (PMID 28450710, 2017). "Two families (family 24 and 27) with PAX6 mutation showed aniridia." (PMID 28450710, 2017). "Classical isolated aniridia is a haploinsufficiency disorder caused by mutations in the Pax6 gene." (PMID 28246397, 2017). "Aniridia primarily occurs due to mutations of PAX6 on band p13 of chromosome 11." (PMID 29238604, 2017). "Previous research had suggested that Pax6 mutations could lead to human aniridia, anterior segment dysgenesis and microphthalmia." (PMID 26744353, 2016). "Therefore, diminished DNA binding of the Pax6 protein likely causes the development of aniridia in Pax6R44Q and Pax6G36R patients." (PMID 25578969, 2015). "In addition, aniridia is a bilateral congenital disease caused by a defect in the PAX6 gene; therefore, additional congenital ocular malformations are often present, including optic nerve hypoplasia, and patients usually have very poor vision and nystagmus." (PMID 26451377, 2015). "Interestingly, PAX6 mutations primarily result in a variable pan-ocular phenotype that includes aniridia (iris hypoplasia), cataract, glaucoma, corneal clouding, foveal dysplasia, and optic nerve hypoplasia." (PMID 25090642, 2014). "When Pax6 was mutated in human it led to microphthalmia, aniridia and pan-ocular disorder." (PMID 24636305, 2014). "Congenital aniridia is a rare condition related to a deficiency in the PAX6 gene expression, which may occur as a result of a family inheritance or a sporadic occurrence." (PMID 27355034, 2014). "Similarly, PAX6 haploinsufficiency in humans results in the pan-ocular eye disorder aniridia that manifests as cataracts, corneal opacification, and retinal anomalies, while compound heterozygosity for PAX6 loss-of-function causes anophthalmia." (PMID 25517354, 2014). "Mutations in the PAX6 gene are detected in the patients with congenital aniridia." (PMID 23799907, 2013). "We also identified a novel PAX6 mutation in a Chinese family with aniridia and congenital ptosis." (PMID 23734086, 2013). "Mutations or intragenic deletions of PAX6 were the major causes of aniridia and iris coloboma, however, rare cases could be associated with large chromosomal deletions or rearrangements." (PMID 24349436, 2013). "In addition, the proband inherited a mutation in PAX6 from his father, who also had congenital aniridia." (PMID 23799907, 2013). "The mutation (c.362C>T) in the PAX6 gene was first identified in patients with aniridia." (PMID 23734086, 2013). "Human aniridia is an inherited eye disease caused by heterozygosity for a defective PAX6 gene." (PMID 23967157, 2013). "In all five Peters anomaly/aniridia families reported here, the clinical phenotype was only noted in the proband and mutations in PAX6, the primary aniridia gene were excluded; in two families, the parent carrying the FOXD3 variant had a ‘lazy eye’ (ambylopia) during childhood." (PMID 22815627, 2012). "We also found four novel PAX6 mutations associated with aniridia." (PMID 22393275, 2012). "The identification of a large number of mutations confirmed the role of PAX6 in human eye disease,and the features of aniridia also reflect the wide expression of PAX6 in the developing eye, including the neurectoderm, the surface ectoderm, and their derivatives." (PMID 22815628, 2012). "Therefore, haplo-insufficiency of the PAX6 gene has been suggested to underlie the aniridia phenotype." (PMID 22815628, 2012). "Various mutations in the paired box gene 6 (PAX6) gene are primarily responsible for aniridia." (PMID 22815628, 2012).